IL1B (interleukin 1 beta)
Diseases named in the same sentence as IL1B in open-access papers (continued):
Sharing a sentence is not in itself a finding about the gene and the disease.
brain inflammation (continued). "To investigate the role of SDF-1 and MCP-1 in mediating NPC migration to IL-1β stimulation, we reasoned that both SDF-1 and MCP-1 released by astrocytes upon IL-1β stimulation are the major attractants for NPC migration in diseased brain or during brain inflammation." (PMID 23210607, 2012). "On the other hand, GSK-3β also functions as a negative regulator of pro-inflammatory cytokine expression and decreased GSK-3β expression may render Pink1−/− mice more vulnerable to TNF-α, IL-1β and LPS-induced brain inflammation." (PMID 21249202, 2011). "Thus, CX3CR1-mediated regulation of IL-1β expression in microglia may play an important role in the resolution of brain inflammation and sickness behavior." (PMID 21167054, 2010). "Pro-inflammatory cytokine levels (IL-1β, IL-6, and TNF-α) in the hippocampus were measured via ELISA to assess brain inflammation in mice." (PMID 41155481, 2025). "Given the link between gut dysbiosis and brain inflammation via the gut-brain axis, we examined key pro-inflammatory markers, including TLR4, TNF-a, and IL-1B." (PMID 41286043, 2025). "Brain inflammation activates microglia and leads to the production of proinflammatory molecules such as TNF-α, IL-1β, and IL-6." (PMID 31444225, 2019). "“Interleukin-1 beta-DISRUPTS-uptake” was extracted from an article, which reported that astrocyte uptake of glutamate is neuroprotective during brain inflammation." (PMID 30587224, 2018). "Upregulation of HO-1 attenuates IL-1β-induced cell migration via inhibition of MMP-9 expression in RBA-1 cells and is therefore a potential strategy for treatment of inflammatory brain diseases." (PMID 29209167, 2017). "Altered IL-1β, IL-6, and TNF-α expression levels activating the STAT3 pathway have been found in brain inflammation models." (PMID 28143489, 2017). "Compared with WT mice, Tim-3−/− mice had reduced ICH-induced brain inflammation with decreased TNF-α and IL-1β, cerebral edema and neurological deficit scores." (PMID 24289479, 2013). "IL-1β and TNF-a are two main proinflammatory cytokines of microglial source, which represent the level of brain inflammation." (PMID 24289479, 2013). "We previously found that SDF-1 increased in HAD patients in an IL-1β-dependent manner, so how does this chemokine and its receptor affect NPC migration in the HAD and other brain inflammatory diseases?" (PMID 23210607, 2012). "The excessive production of LPS by the gut microbiota triggers the production of inflammatory cytokines such as IL-6, IL-1β, and TNF-α, further disrupting the HPA axis, increasing brain inflammation, and promoting neurodegeneration, which impairs hippocampal neurogenesis." (PMID 40077516, 2025). "Compared to controls (0.1% BSA in 0.9% NaCl), a significant increase of genes related with glia activation (Gfap and Cd68 but not Iba1) but not with brain inflammation (Il-6, Il-1β) was observed at 24 h post-injection." (PMID 35203276, 2022). "Thus, the results indicate the neuroprotective effect of chondroitin sulfate as an anti-inflammatory agent by suppressing the NF-kB and decreasing the inflammatory mediators (IL-1β, IL-6, and TNF-alpha) that act as biomarkers of brain inflammation." (PMID 34833865, 2021). "IL-1β induces inflammation in the periphery, while IL-1β inside the BBB acts as a transmitter substance which causes behavioural effects without major brain inflammation." (PMID 22253903, 2012). "In addition, the mRNA expression levels of inflammatory cytokines (Il-6, Il-8, Il-10, Il-18, Il-1β, and Tnf-α) in GPS-infected mice were significantly increased compared to the control group (p < 0.05), which indicated that GPS successfully induced brain inflammation in mice." (PMID 38927100, 2024).
chondrosarcoma (50 papers, 2005 to 2025). A malignant cartilaginous matrix-producing mesenchymal neoplasm arising from the bone and soft tissue. "Since human chondrocytes can be cultured for limited generation, the level of NEAT1_2 significantly declined under IL-1β-caused stress in a chondrosarcoma cell line, SW1353, which will be used as the model to carry out further investigation." (PMID 38137512, 2023). "RANKL production leads to cartilage destruction, as increase in the RANKL/OPG ratio is associated with high MMP-13 synthesis in IL-1β-triggered SW1353 chondrosarcoma cells." (PMID 31546898, 2019). "In chondrosarcoma, IL-1β has been found to regulate p38, which in turn promotes RUNX2-mediated MMP-13 transcription and translation, playing a crucial role in tumor progression." (PMID 40386045, 2025). "PDREP reduced the expression of inflammatory cytokines, mediators, and MMPs in IL-1β-induced SW1353 chondrosarcoma cells and MIA-induced OA rat models, and it also decreased phosphorylation levels of MAPKs and NF-κB proteins." (PMID 39599668, 2024). "To determine the molecular effects of PBSL, we used interleukin‐1β (IL‐1β)‐induced SW1353 chondrosarcoma or lipopolysaccharide (LPS)‐stimulated macrophages." (PMID 38107146, 2023). "In this study, we used a monosodium iodoacetate (MIA)‐induced OA mouse model and interleukin‐1β (IL‐1β)‐induced SW1353 chondrosarcoma cells or lipopolysaccharide (LPS)‐stimulated macrophages in vitro models to study the effects of PBSL on OA." (PMID 38107146, 2023). "CEMIP also mediated IL-1β expression through Erk pathway activation and NF-KB translocation in chondrosarcoma cell line." (PMID 35474501, 2022). "In the present study, we used 10 ng/ml of IL-1β to simulate the OA environment in human chondrosarcoma cell line SW1353 and C28/I2 cells." (PMID 36133743, 2022). "Ok-PDRN displayed anti-inflammatory activity in a human chondrosarcoma cell line stimulated by IL-1β (10 ng/mL), as well as RAW 264.7 cells stimulated by a combination of zoledronic acid (ZA, 10 μM) and LPS (0.1 μg/mL)." (PMID 34067499, 2021). "IL‐1β exhibited a dose‐dependent growth inhibitory effect on both the primary OA chondrocytes and chondrosarcoma cell line SW1353." (PMID 34037306, 2021). "Whilst downregulation of MMP3 and MMP13 has been reported to be indicative of the chondroprotective action of Icariin in SW1353 chondrosarcoma cells stimulated with IL-1β." (PMID 33177241, 2020). "Further, to explore the protective efficacy of LI13019F1, we tested the modulation of SOX-9 expression in IL-1β-induced SW1353 human chondrosarcoma cells." (PMID 32565872, 2020). "The formula was tested in the context of positive properties against OA, via in vitro experiments on cellular IL-1β-stimulated chondrosarcoma, SW1353 cell model." (PMID 32340224, 2020). "The increases in IL-1β-treated human chondrosarcoma cell line SW1353 were 65.6% for MMP-1, 196.5% for MMP-3 and 119.3% for MMP-13." (PMID 33321982, 2020). "On average, 1, 2.5, and 5 μg/mL doses of LI13019F1 protected 34.62, 47.66, and 62.29% SW1353 human chondrosarcoma cells from IL-1β induced SOX-9 depletion, respectively." (PMID 32565872, 2020). "ADAMTS-4 and ADAMTS-5 levels were increased by 83.7 and 82.5%, respectively, in IL-1β-treated human chondrosarcoma cell line SW1353." (PMID 33321982, 2020). "Relative to the levels for IL-1β-treated human chondrosarcoma cell line SW1353, the expressions of MMP-1, MMP-3 and MMP-13 were decreased dose dependently in the 20 μg/mL CZE and 0.4 μg/mL linarin treatment." (PMID 33321982, 2020). "SOX9 expression was reduced by 36.6% in IL-1β-treated human chondrosarcoma cell line SW1353 and this downregulation was reversed dose dependently in the 20 μg/mL CZE and 0.4 μg/mL linarin treatments." (PMID 33321982, 2020). "Compared with IL-1β-treated human chondrosarcoma cell line SW1353, ADAMTS-4 and ADAMTS-5 expression were decreased dose dependently in the 20 μg/mL CZE and 0.4 μg/mL linarin treatments." (PMID 33321982, 2020).
chondrosarcoma (continued). "To evaluate the effects of vitamin B6 in cartilage cells, we treated differentiated mesenchymal stem cells and the SW1353 chondrosarcoma cell line with vitamin B6 in the presence of IL1β, the inflammatory cytokine involved in OA." (PMID 31683926, 2019). "In SW1353 chondrosarcoma cells, IL-1β (interleukin-1β) induces overexpression of IL-6 (interleukin-6), PGE2 (prostaglandin E2) and Cox-2 (cyclooxygenase 2), which, in turn, activate a series of MMPs, such as MMP-1 and MMP-13." (PMID 31546898, 2019). "We have been generally successful in our attempt to the protective effects of pseudoshikonin I against IL-1β-induced MMPs production and mRNA expression in vitro using human chondrosarcoma cells." (PMID 27548143, 2016). "Apart from cAMP, IL-1β has a critical role in inducing the expression of MMP-7 in shear-activated human chondrosarcoma cells." (PMID 25823818, 2015). "Because of the elevated AKT, ERK1/2 and p38 phosphorylation levels in shear stress-, forskolin- and IL-1β-stimulated chondrosarcoma cells, we examined the potential contributions of AKT, ERK1/2 and p38 to regulating the activities of c-Jun and NF-κB." (PMID 25823818, 2015). "As microenvironment-derived IL-1β is required for invasion and angiogenesis in malignant tumors, also in chondrosarcomas, we investigated IL-1β-induced signal transduction and VEGF-A expression in C3842 and SW1353 chondrosarcoma cells." (PMID 24901233, 2014). "We defined an appropriate Curcumin concentration and incubation time prior to IL-1β treatment to block IL-1 signaling in chondrosarcoma cells." (PMID 24901233, 2014). "The third most up-regulated gene after IL-1β was ICAM1, which is a cell adhesion molecule that was recently associated with cell motility and migration of chondrosarcoma cells." (PMID 24901233, 2014). "In our previous studies we showed that IL-1β treatment leads to increased VEGF-A expression in C3842 chondrosarcoma cells." (PMID 24901233, 2014). "In this study we additionally demonstrated IL-1β-induced VEGF-A expression in SW1353 chondrosarcoma cells." (PMID 24901233, 2014). "To analyze the effect of IL-1β on VEGF-A expression we treated chondrosarcoma cells with IL-1β (10 ng/ml)." (PMID 24901233, 2014). "Previously, we published that IL-1β induces MMP gene expression in non-small cell lung carcinoma and chondrosarcoma cells, and that IL-1β induction of MMP gene expression in these cancer lines is dependent on the transcriptional activity of the CEBPβ." (PMID 23342250, 2012). "We used real-time reverse transcription-polymerase chain reaction to measure LG268- and rosiglitazone-mediated inhibition of MMP gene transcription in IL-1-β-treated SW-1353 chondrosarcoma cells." (PMID 19046432, 2008). "Fluid shear stress activates PI3-K/AKT, ERK1/2, and p38 pathways in human chondrosarcoma cells via a cAMP- and IL-1β-dependent mechanism, as evidenced by the inhibition of AKT, ERK1/2 and p38 phosphorylation by a cAMP inhibitor and an anti-IL-1β neutralizing antibody." (PMID 25823818, 2015). "Similar observations were made using forskolin- or IL-1β-stimulated human chondrosarcoma cells." (PMID 25823818, 2015). "Interestingly, we recently reported that fluid shear increases the accumulation of both cAMP and IL-1β in human chondrosarcoma cells." (PMID 25823818, 2015). "Therefore, both cAMP and IL-1β are key signaling molecules in mediating shear-induced MMP-7 expression in human chondrosarcoma cells." (PMID 25823818, 2015). "Also IL-1β and IL-1α were induced by IL-1β treatment, showing a feed-forward effect and demonstrating that stimulated chondrosarcoma cells are able to produce these cytokines." (PMID 24901233, 2014). "Up-regulation of MMP-1 and MMP-13 by IL-1β was previously demonstrated in chondrosarcoma cells." (PMID 24901233, 2014). "Therefore, we assume that the regulation of IL-1β induced VEGF-A expression is a therapeutic option in chondrosarcomas." (PMID 24901233, 2014).
chondrosarcoma (continued). "In chondrosarcoma cells treated with IL-1β nuclear translocation of NF-κB was evident." (PMID 24901233, 2014). "Previously we described the regulation of VEGF-A expression by IL-1β in chondrosarcoma cells." (PMID 24901233, 2014). "Additionally, we showed that IL-1β induced angiogenesis by cell culture supernatants of chondrosarcoma cells was blocked by Curcumin using an in vitro tube forming assay." (PMID 24901233, 2014). "Therefore, in this study, we have chosen to use ribosomal profiling and proteomic approaches to examine how translation is altered in an in vitro model of chondrocyte response using the SW1353 chondrosarcoma line stimulated with the inflammatory cytokine IL-1β." (PMID 31300557, 2019). "In addition, RIAA inhibited NF-κB-mediated inflammatory markers in various cell models, including nitric oxide in LPS-stimulated RAW 264.7 cells, RANKL-mediated TRAP activity in transformed osteoclasts, and TNF-α/IL-1β-mediated MMP-13 expression in SW1353 human chondrosarcoma cells." (PMID 19712471, 2009). "According to the study, Rb1 treatment (80 μM) for 24 h decreased IL-1β-induced NO production by 46% compared to the IL-1β treated SW1353 cells, a kind of human chondrosarcoma cell lines." (PMID 40507179, 2025). "In an OA CC model, IL-1β induced the expression of the proinflammatory factors TNF-α, IL-1β, and IL-6 in the human chondrosarcoma cell line SW1353 and normal human CCs (C28/I2), which was partially reversed by TXNIP overexpression." (PMID 36059548, 2022). "ALE and cynaropicrin both suppress IL-1β-induced NF-κB signaling and inhibit the production of MMP13 in the human chondrosarcoma cell line OUMS-27." (PMID 34444810, 2021). "The chondrosarcoma cell line, SW1353, stimulated by the combined cytokines, IL-1β and IL-17A, was selected to evaluate the effects of KP extract and its major components at a cellular level." (PMID 33799537, 2021). "Taken together, these data demonstrated that the IL‐1β‐treated primary OA chondrocyte and SW1353 chondrosarcoma cells served as a robust in vitro model mimicking the degenerative effect of osteoarthritic cartilage." (PMID 34037306, 2021). "We first verified that transcriptional expression of MMP1, MMP3, MMP13, and ADAMTS4 was upregulated by IL-1β or TNF-α and repressed by I-BET151 in a human chondrosarcoma cell line (SW1353)." (PMID 30786900, 2019). "Specifically, shear-induced cAMP and IL-1β activate PI3-K, ERK1/2 and p38 signaling pathways, which lead to the synthesis of MMP-7 via transactivating NF-κB and c-Jun in human chondrosarcoma cells." (PMID 25823818, 2015). "Specifically, fluid shear stress induces the synthesis of cAMP and IL-1β, which in turn activate PI3-K-, ERK1/2-, p38-dependent signaling pathways leading to MMP-7 induction via transactivation of NF-κB and c-Jun in human chondrosarcoma cells." (PMID 25823818, 2015). "Though PI3/Akt signalling pathway can be activated by TNF-α in human smooth muscle cells or IL-1β in rat brain astrocytes, our results are consistent with BDNF-induced migration in human chondrosarcoma through a transducing signal involving TrkB." (PMID 25418464, 2014). "IL-1β stimulated MMP-9 and MMP-2 in chondrosarcoma cells, enhanced levels of both MMPs at 1 ng/ml but decreased levels at 25 ng/ml in fibrosarcoma, inhibited MMP-2 and enhanced MMP-9 at 1 and 10 ng/ml and downregulated at 25 ng/ml in liposarcoma cells." (PMID 24085323, 2013). "Because MMPs production is induced by IL-1β, we evaluated the inhibitory effects of SOCS1 on MMPs synthesis by altering SOCS1 expression levels in the SW1353 chondrosarcoma cells." (PMID 24238405, 2013). "We recently described the ability of retinoid X receptor (RXR) ligand LG100268 (LG268) to inhibit interleukin-1-beta (IL-1-β)-driven matrix metalloproteinase-1 (MMP-1) and MMP-13 gene expression in SW-1353 chondrosarcoma cells." (PMID 19046432, 2008).
chondrosarcoma (continued). "MMP-3 and MMP-13 gene expression induced by IL-1β, TNF-α and IL-17 was downregulated by mithramycin in human chondrosarcoma SW1353 cells and in primary human and bovine femoral head chondrocytes." (PMID 15987479, 2005). "Meanwhile, in OUMS-27 cells (a human chondrosarcoma cell line), both TNF-α, IL-1β, and IL-6 could upregulate KIAA1199 expression." (PMID 37569797, 2023). "MMP-1 and MMP-3 expression in IL-1β-stimulated chondrosarcoma cells was suppressed by p38 and ERK inhibitors but not by JNK inhibitor, and MMP-13 expression was suppressed by p38 and JNK inhibitors but not ERK inhibitor." (PMID 32213810, 2020). "Notably, miR-18a was remarkably increased both in cartilage tissues from rat knee OA model with intra-articular injection of IL-1β and in human ACs and SW1353 cells (a human chondrosarcoma cell line) treated with IL-1β in vitro." (PMID 33144571, 2020). "About CSF2, which was the most up-regulated gene by IL-1β, no reports on chondrosarcomas have been published to our knowledge so far." (PMID 24901233, 2014). "Collectively, our data suggest that fluid shear induces the accumulation of both cAMP and IL-1β, which in turn activate the AKT, ERK1/2 and p38 signaling pathways that are responsible for the elevated MMP-7 expression and enzymatic activity in himan chondrosarcoma cells." (PMID 25823818, 2015). "Previous studies have shown that HA (800 kDa and higher) suppressed IL-1β-stimulated production of collagenases (MMP-1 and MMP-13) by human articular cartilage explants and isolated chondrocytes, as well as a human chondrosarcoma cell line, through down-regulation of phospho-p38 MAPK." (PMID 23889808, 2013). "MMP-2 and-9 expression of chondrosarcoma and fibrosarcoma cells treated with IL-1β 10 ng/ml were downregulated by NM treatment in a dose-dependent manner with MMP-2 block at 1000 μg/ml NM and MMP-9 total block at 100 μg/ml NM in fibrosarcoma and at 1000 μg/ml in chondrosarcoma." (PMID 24085323, 2013). "Interestingly, the adenylate cyclase inhibitor SQ22536 or an anti-IL-1β antibody alone were effective in suppressing the shear-induced upregulation of AKT, ERK1/2 and p38 phosphorylation, which result in MMP-7 suppression in shear-activated SW1353 chondrosarcoma cells." (PMID 25823818, 2015). "Furthermore, it has been reported that in the human chondrosarcoma cell lines C3842 and OUMS‐27, the inflammatory stimulus IL‐1β reduced ADAMTS1 mRNA levels, while hypoxia did not alter ADAMTS1 mRNA in C3842." (PMID 40864881, 2025).